CD274 (CD274 molecule)
Diseases named in the same sentence as CD274 in open-access papers (continued):
Sharing a sentence is not in itself a finding about the gene and the disease.
tumor (continued). "Furthermore, PD-L1/CD274 silencing on DC could enhance T-cell responses leading to tumor clearance, which is in accordance with several studies demonstrating the advantages of knocking down PD-L1/CD274 regarding the efficacy of DC vaccine therapy." (PMID 33066260, 2020). "Interestingly, CD274, also referred to as the immune checkpoint protein programmed death-ligand 1 (PD-L1), was one of the few genes that remained upregulated at 6 w p.i. compared to 1 w p.i., suggesting that the PD-L1 axis plays a critical role in 4T1 tumor progression." (PMID 31921184, 2019). "The investigators found that poor tumor perfusion, as measured by multiparametric methods, correlated with high expression levels of vascular endothelial growth factor A (VEGFA) and immune checkpoints, cluster of differentiation 274 (CD274) and cytotoxic T-lymphocyte-associated-protein 4 (CTLA4)." (PMID 30591628, 2018). "If PCRT acts like PD-1 inhibitors, CD274 (PD-L1) expressed tumor might better respond to PCRT." (PMID 29108360, 2017). "In addition, we demonstrate that blockade of the PDCD1/CD274 pathway leads to increased tumour cell clearance in the TCL1tg mouse model and might hence represent a promising new option in treatment of this disease." (PMID 25940792, 2015). "Its ligand is PD-L1, a transmembrane glycoprotein also known as cluster differentiation 274 (CD274), that is expressed primarily on dendritic cells and various types of tumor cells." (PMID 41356798, 2026). "EATL containing more abundant macrophages was enriched in inflammatory response signatures, with upregulation of CD274, CXCL13, and IDO1 transcripts, suggesting an immunosuppressive tumor microenvironment." (PMID 41057685, 2026). "Upon engagement with its ligands, PD-L1 (CD274, B7-H1) and PD-L2 (CD273, B7-DC) expressed on tumor cells or APCs, PD-1 transduces inhibitory signals that dampen cytotoxic CD8+ T cell activation and contribute to tumor immune evasion in cancer." (PMID 41486149, 2026). "PD-L1 (CD274) binds to PD-1, resulting in exhaustion of CD8+ cytotoxic T cells that have entered the tumor." (PMID 41522360, 2026). "Its ligands, PD-L1 (CD274, B7-H1) and PD-L2 (CD273, B7-DC), are widely expressed on tumor cells, immune-presenting cells, and stromal cells within peritumoral environment." (PMID 40861443, 2025). "Unexpectedly, ETS1 also orchestrated an immune-cold tumor microenvironment by transcriptionally activating both STAT1 and PD-L1 (CD274) genes, suppressing T lymphocyte infiltration, and elevating immune checkpoint molecules." (PMID 40777467, 2025). "Several transcripts associated with immunological checkpoints, such as SIGLEC15, PDCD1LG2 (PD-L2), TIGIT, PDCD1 (PD-1), CD274 (PD-L1), CTLA4, LAG3, and HAVCR2 (TIM3), play a crucial role in tumor immune evasion." (PMID 40893939, 2025). "Programmed death ligand 1 (PD-L1; also known as CD274 and B7-H1) plays an important role in immune suppression and tumor immune evasion." (PMID 40002814, 2025). "The higher expression of CD274 and CTLA4 in low-risk patients suggests that they may benefit more from immune checkpoint inhibitors, as these molecules help regulate immune response and prevent the release of excessive pro-inflammatory cytokines, thereby potentially limiting tumor progression." (PMID 40103813, 2025). "Numerous transcripts related to immunological checkpoints, including SIGLEC15, PDCD1LG2 (PD-L2), TIGIT, PDCD1 (PD-1), CD274 (PD-L1), CTLA4, LAG3, and HAVCR2 (TIM3), are integral to tumor immune evasion mechanisms." (PMID 41194934, 2025). "In sample HCC4, the tumor areas commonly expressed high IDO1, low PD‐L1 and CD274, and very low CTLA4." (PMID 41057994, 2025). "In group 0, several immune checkpoint and pro-inflammatory genes, including PDCD1LG2 (PD-L2), CD274 (PD-L1), HLA-A, CXCL10, and CD163, displayed relatively high expression, suggesting a more inflamed tumor microenvironment." (PMID 41517303, 2025).
tumor (continued). "The interaction between programmed death ligand 1 (PD-L1; also called CD274 or B7-H1) on tumor cells and programmed cell death 1 (PD-1) on activated T cells regulates immune evasion, leading to T cell exhaustion." (PMID 40779629, 2025). "PD-L1 (B7-H1 or CD274), expressed on the surface of tumor cells as a ligand for PD-1, can inhibit T cell activation and negatively regulate the adaptive immune response, thereby enabling tumors to evade immune surveillance." (PMID 40959085, 2025). "This aligns with our broader analysis implicating chemokine ligands (CCL family), immune checkpoints (PD‐L1/CD274, PDCD1LG2, HAVCR2), and cell surface markers in shaping tumor immune phenotypes." (PMID 40693457, 2025). "It both supports tumor energy by recycling nutrients like glutamine and suppresses anti-tumor immune responses by increasing immune checkpoint molecules such as CD274/PD-L1." (PMID 40851276, 2025). "To establish a foundational understanding of PSD3, CD274 (PD-L1), and TNFSF18 expression in cancer, we first conducted a comparative analysis of their mRNA levels across a wide array of tumor types using The Cancer Genome Atlas (TCGA) datasets." (PMID 40895529, 2025). "In contrast, the tumor areas commonly expressed high CTLA4, low PD‐L1 and CD274, and very low IDO1 in sample HCC3." (PMID 41057994, 2025). "This integrated approach enables a more comprehensive understanding of PSD3, CD274, and TNFSF18 in the context of the ESCC tumor immune microenvironment." (PMID 40895529, 2025). "Subsequent CellChat analysis revealed enhanced interactions between ACACA-high tumor cells and CD8+ T cells, primarily via secreted signaling pathways like the macrophage migration inhibitory factor (MIF) axis (MIF-CD74+CXCR4, MIF-(CD274+CD44))." (PMID 41169354, 2025). "IL-6 and IL-1β can enhance CD274 expression in tumor cells by activating the JAK2/STAT3 signaling pathway, making it difficult to be recognized by T cells and facilitating tumor immune evasion." (PMID 39911394, 2025). "These resistant TAMs preferentially express angiogenic (VEGFA) and immunosuppressive (CD274, ARG1) genes and promote tumor vascularization." (PMID 41450739, 2025). "The first major finding of our study is the consistently elevated expression of CD274 and TNFSF18 in ESCC tumor tissues compared to normal esophageal epithelium, as observed in both the TCGA and GEO datasets." (PMID 40895529, 2025). "In tumor immune evasion, PD-L1 (or CD274) is expressed on the surface of various cells, including macrophages, APCs, and DCs and is found at elevated levels on tumor cells as part of their immune tolerance mechanism." (PMID 40006624, 2025). "Subsequently, we examined the mRNA levels of CCL5, CD274, CXCL10, CXCL11, and CCL2 in MDA‐MB‐231 and 4T1 cells and tumor tissues." (PMID 39585774, 2025). "PD-L1, also known as CD274 or B7H1, is expressed on tumor cells and plays an important role in tumor immune escape and the formation of a permissive immune microenvironment through various mechanisms." (PMID 40688872, 2025). "An analysis of these immune checkpoints in tumor and normal samples revealed significant differences in the expression of CD200, CD274, TIGIT, TNFRSF25, and TNFSF15 between the two groups (P < 0.05)." (PMID 40666524, 2025). "Programmed cell death ligand 1 (PD-L1), also referred to as CD274, is a transmembrane protein that is often expressed on tumor cells, where it interacts with the PD-1 receptor on T cells, leading to immune suppression." (PMID 39858472, 2025). "Its interaction with ligands PD-L1 (CD274) and PD-L2, expressed on tumor cells and immune cells within the tumor microenvironment (TME), attenuates T-cell receptor (TCR) signaling and co-stimulatory pathways (e.g., CD28), promoting immune escape." (PMID 40649207, 2025).
tumor (continued). "CD274 and TNFSF18 were consistently up-regulated in tumor tissues across both TCGA and GEO cohorts, whereas PSD3 exhibited a context-dependent pattern, showing significant up-regulation in TCGA but no differential expression in GEO." (PMID 40895529, 2025). "Herein, several KLF4-assocaited genes, C10orf54 and CD274 were correlated with tumor suppression, while others, including CX3CL1, TNFRSF4, and IL1A, were correlated with tumor stimulation." (PMID 40299916, 2025). "Based on the result derived from GEPIA, the expression of genes, including Cd3e, Cd274 (PDL-1), Wt1, Fate, Gbp2, and Cybb were significantly upregulated in the GBM tumor compared to the normal brain." (PMID 41282050, 2025). "To assess the potential tumor suppressor role of APOB in HCC, we employed the Spearman correlation coefficient to evaluate the relationship between APOB and CD274, PDCD1, and CTLA4." (PMID 38310202, 2024). "AXL has also been implicated in the regulation of immune checkpoint molecules, including PD-L1 (CD274, PDCD1LG1 or B7-H1), on tumor cells or immune cells." (PMID 39367387, 2024). "The upregulation of CD274, IDO1, etc. on the tumor surface by T cell activation and IFN-α/IFN-γ stimulation has been demonstrated." (PMID 38629071, 2024). "MDSCs can indirectly enhance their own anti-tumor immune effects by producing iNOS, IL-10, TGF-β, and CD274, thereby promoting Treg development." (PMID 39227970, 2024). "Bondage of β-catenin/Tcf/Lef complex to the promoter of CD274 gene induces PD-L1 expression on tumor cells, and the impact of WNT/β-catenin on PD-L1 activation is indicative of the key role of this signaling in regulation of tumor immune landscape." (PMID 38280119, 2024). "To explore the correlation between Plek2 knockdown and immunomodulatory molecules, we collected tumor tissues from C57BL/6 mice bearing tumors and extracted RNA for RT-PCR analysis of Cd276, Cd274, and Lgals9 expression." (PMID 39546161, 2024). "PD-L1, also known as Cluster of Differentiation 274 (CD274), is expressed in numerous tumor cells, including NSCLC and antigen-presenting cells (APCs), and is one of the primary ligands of the PD-1 receptor." (PMID 38398135, 2024). "As expected, hot tumor regions displayed markedly higher anti-PD1 favor scores, higher expression, and lower methylation for genes CD274 and CTLA4." (PMID 38803565, 2024). "The expression of ligands, including TNFRSF14, CD274, and LGALS9, on tumor cells increased in the LN-out group." (PMID 38519500, 2024). "Third, the correlation module results showed that DSN1 was related to some well-known tumor immune-related biomarkers, such as PDCD1, CD274, PDCD1LG2, and CTLA4." (PMID 39555702, 2024). "IDO1 is positively correlated with CD274, TNFRSF9, TNFRSF4, PDCD1LG2, IDO2, and CD48 in many tumor types." (PMID 38539263, 2024). "Subsequently, we employed immunohistochemistry(IHC) and Western Blot (WB) to quantify CD274 protein expression levels in Fuhrman I + II (n = 13) and Fuhrman III + IV (n = 17) tumour tissues, as well as their paired normal control tissues (n = 13)." (PMID 38802631, 2024). "Further database analysis (TIMER2.0) showed that PDCD1 gene expression was positively correlated with the levels of immunosuppressive genes (CD274, PDCD1LG2, TGFB1, and IL10) in most human tumor types." (PMID 38441961, 2024). "Meanwhile, several important ICP genes, such as CD274, CTLA4, CD276, etc. were highly expressed in the PS1 and PS2 subtypes, indicating an immunosuppressive tumor microenvironment in these patients, and they were more likely to be benefit from ICIs." (PMID 38672082, 2024). "Programmed death receptor-1 ligand (PD-L1, CD274) is a well-known immunosuppressive molecule that can mediate the immune escape of tumor cells." (PMID 39668828, 2024). "Specifically, we found that in EC, the MMP score was significantly positively correlated with CAF, CD274, the stromal score, immune score, STIMATE score, and TIDE, but negatively correlated with tumour purity." (PMID 38911387, 2024).
tumor (continued). "By investigating LR interactions involving immunomodulatory targets (CRI-iAtlas), we identified interactions between CD274 (PD-L1), its receptor PDCD1 (PD-1) and its costimulator CD80 (B7-1) exclusively in RP-like tumours." (PMID 37758326, 2024). "In particular, several genes involved in tumor cell immunogenicity were deregulated, such as CD274 coding for PD-L1, which was induced." (PMID 38581044, 2024). "The results demonstrated a positive correlation between FANCD2 and immune checkpoints in most tumor tissues, including CTLA4, HAVCR2, LAG3, PDCD1, PDCD1LG2, SIGLEC15, TIGIT, and particularly CD274." (PMID 38443946, 2024). "CAA-derived CXCL8 remodeled the tumor immune microenvironment not only by suppressing CD4+ T and CD8+ T immune cell infiltration but also by upregulating CD274 expression in TNBC." (PMID 37898619, 2023). "We found that in the PTEN low-expression group, there was a significant decrease in the expression of some immune checkpoints, including CD276, CD274, NRP1, and the TNFRSF family, that are closely involved in immunosuppressive signals in HCC tumor." (PMID 36861063, 2023). "Simultaneously blocking CD274 (programmed death ligand 1, PD-L1, or B7-H1) and CD47 checkpoints on CTCs by corresponding antibodies enhances the inhibition of tumor growth." (PMID 37371863, 2023). "An immune checkpoint protein called Programmed cell-death ligand 1 (PD-L1, B7-H1, CD274) has been found in various cells, including tumor cells and some immune cells." (PMID 37736550, 2023). "We investigated the role of SV in CD274 UTR region in regulating the immune microenvironment of tumors and the immune escape behavior of tumor cells from a cytological perspective using multiplex immunofluorescence (mIF)." (PMID 36717553, 2023). "PD-L1 (CD274) is highly expressed in various cancers, including NSCLC, where it plays an important role in tumor growth and progression." (PMID 37046851, 2023). "To investigate the immune profiles of c-Scorehi tumors across the 25 TCGA tumor types, we evaluated immunomodulatory genes involved in immune checkpoint blockade response, (CD274 [PD-L1], PDCD1 [PD-1], HAVCR2 [TIM3], LAG3, TIGIT, CTLA4, and FASLG)." (PMID 37558751, 2023). "Consistently, the corresponding immune checkpoint ligands CD274 (PD‐L1) and PDCD1LG2 (PD‐L2) were barely expressed in either cancer cells or other infiltrating cells in the tumor microenvironment." (PMID 36529697, 2023). "As secondary analyses, we examined statistical interaction between tumor CD274 expression and MSI status for tumor F. nucleatum status." (PMID 37538192, 2023). "According to studies, EBVaGC has been shown to contribute to the advancement of cancer by overexpressing genes such as PD-L1 (also known as CD274) and enhancing lymphocytosis in the tumor environment." (PMID 38144298, 2023). "The associations of mRNA expression between CRABP2 and three immune checkpoint molecules (PDCD1, CD274 and CTLA4) were examined in 33 different tumor types from the TCGA database using the TIMER2.0 and Xiantao tools." (PMID 38186580, 2023). "PD‐1 ligand 1 (PDL1, also called B7‐H1 or CD274) and PDL2 (also called B7‐DC or CD273) are expressed either constitutively or in response to exposure to interferon γ (IFN‐γ) by many tumor cells." (PMID 37476068, 2023). "The expression of its ligands, programmed death ligand 1 (CD274, PD-L1) and programmed death ligand 2 (PDCD1LG2, PD-L2, CD273), is induced by inflammatory cytokines released after TR activation, on tumor cells." (PMID 37215135, 2023). "PD-L1 (also known as B7-H1 or CD274), one of the ligands of PD-1, binds to PD-1 on effector T cells for immunosuppressive functions and is widely expressed in a variety of tumor cells; the high expression of PD-L1 also predicts poor prognosis." (PMID 37055849, 2023).
tumor (continued). "The relationship between the expression levels of CD274, TIGIT, PDCD1, CTLA4 and LAG3 in tumor tissues of normal and LUAD patients and the relationship between each gene and the survival rate of LUAD patients." (PMID 36959799, 2023). "We further analyzed the tumor microenvironment between different RiskScore groups, and it was also apparent that the expression of PDCD1, CD274, CTLA-4, HAVCR2 and LAG3 in the low-RiskScore group was relatively high." (PMID 37154982, 2023). "The relationship between PIMREG and immune checkpoints, including PD1 (PDCD1), PD1-L1 (CD274), and CTLA-4, which play a crucial role in tumor immune evasion, was assessed." (PMID 37483962, 2023). "Increased infiltration of CD8+ T immune cells, activation of immune checkpoints, such as CD274 and LAG3, and high immune scores play a crucial role in hot tumours." (PMID 37006256, 2023). "Consistently, the corresponding immune checkpoint ligands CD274 (PD‐L1) and PDCD1LG2 (PD‐L2) were barely expressed in both cancer cells and other infiltrating immune/stromal cells in the tumor microenvironment." (PMID 36529697, 2023). "In the field of tumor immunotherapy research, the six immune checkpoints PDCD1, CD274, CTLA-4, LAG-3, TIGIT, and HAVCR2 can inhibit the proliferation, activation and effector functions of T cells, and maintain the immune homeostasis in the body." (PMID 37810780, 2023). "The gene expression profile in CMS3 TME of KRASmut shows upregulation of CD40, CTLA4, ARG1, STAT3, IDO, and CD274, making it a key regulator of immune suppression in TME regions surrounding the KRASmut tumor." (PMID 36831441, 2023). "(H) Expression of Cd274 (PD-L1) on isolated CD45+ cells using Nanostring Immune Exhaustion panel comparing draining lymph nodes (dLN) and tumors from Met-1 Kin1-WT and Kin1-NULL tumor bearing mice." (PMID 36883731, 2023). "PD-L1 (CD274) and CD86 (B7-2) are predominantly expressed on tumor cells or antigen-presenting cells in the TME." (PMID 37998737, 2023). "Including only PDCD1-CD274 as an inhibitor (purple lines) resulted in a poor fit to the number of CTLs counted inside the tumor, as well as the dynamics of PDCD1 and CD274 themselves." (PMID 37182110, 2023). "Among the tumor cell lines, MDA-MB-231 presented the highest levels of CD274 (PD-L1) and PDCD1LG2 (PD-L2) expression compared to all cell lines (all p < 0.014)." (PMID 36901916, 2023). "NPM::ALK-STAT3 signaling in ALK+ ALCL induces expression of transforming growth factor beta (TGF-β), IL-10, and cell surface receptor PD-L1 (CD274, B7H1), creating an immunosuppressive tumor microenvironment." (PMID 37810974, 2023). "More specifically, CD274 expression was highest in Macro CXCL10 and Macro CXCL10 derived from responding tumours displayed higher CD274 expression (Fig. 5cbottom)." (PMID 38030622, 2023). "Under steady-state conditions, LECs express high levels of T-cell inhibitory molecules, including PD-L1 (CD274), which induces apoptosis in tumour-specific CD8+ T cells." (PMID 37433897, 2023). "Moreover, downregulation of the PD-L1 mRNA (CD274 gene) in SR59230A-treated tumor compared to vehicle condition and upregulation of different other genes involved in immune-related processes corroborated the correlation between β3-AR and the immune-checkpoint PD-L1 observed at protein level." (PMID 36854895, 2023). "PD-L1, also known as CD274 or B7-H1, is a ligand of PD-1 and is widely expressed in most tumor cells, macrophages, activated T cells, B cells, monocytes, and endothelial cells." (PMID 37313405, 2023). "Notable, the expression of multiple immune checkpoints in the tumor issue is significantly high such as PDCD1, CD274, and TIM3, which suggests Cluster B is a typical immune‐inflamed tumor." (PMID 35801342, 2023). "For exhaustion related to the CD274/PDCD1 axis, this is clearly justified because IFNG can induce upregulation of CD274 on tumor cells." (PMID 37182110, 2023).